SLC26A9 (solute carrier family 26 member 9)
Description:
Ion transporter that can act both as an ion channel and anion exchanger. Mainly acts as a chloride channel, which mediate uncoupled chloride anion transport in an alternate-access mechanism where a saturable binding site is alternately exposed to either one or the other side of the membrane. Also acts as a DIDS- and thiosulfate-sensitive anion exchanger the exchange of chloride for bicarbonate ions across the cell membrane.
Tractability: Antibody: UniProt places it where antibodies can reach, with high confidence; its Gene Ontology location is reachable by antibodies, with high confidence; UniProt predicts a signal peptide or a membrane-spanning region.
Target class: SLC26 family of anion exchangers; Electrochemical transporter; SLC superfamily of solute carriers; Transporter
Gene: Protein-coding gene on chromosome 1 (205,913,048 to 205,943,460, reverse strand). Ensembl gene ENSG00000174502.
Subcellular location: Cell membrane; Endomembrane system
Subcellular location (Human Protein Atlas): Cell Junctions
Pathways (Reactome):
Transport of small molecules: Inorganic anion exchange by SLC26 transporters
Gene Ontology:
Molecular function: ATPase binding; chloride channel activity; solute:inorganic anion antiporter activity; chloride:bicarbonate antiporter activity; oxalate transmembrane transporter activity; sulfate transmembrane transporter activity
Biological process: chloride transmembrane transport; chloride transport; monoatomic anion transport; positive regulation of gene expression; sulfate transmembrane transport; transmembrane transport; oxalate transport
Cellular component: apical plasma membrane; cell surface; endomembrane system; endoplasmic reticulum membrane; endosome membrane; extracellular exosome; Golgi membrane; plasma membrane; membrane
Genetic constraint (gnomAD): Loss-of-function variants: 46 observed, 91.35 expected, observed/expected ratio (o/e) 0.5, 90% interval 0.4 to 0.64. The upper end of that interval is the gene's LOEUF score, 0.64, which puts it in group 2 of 6, group 1 being the genes least tolerant of losing a copy. Missense variants: 927 observed, 1,051.3 expected, observed/expected ratio (o/e) 0.88, 90% interval 0.83 to 0.93. Synonymous variants: 437 observed, 421.12 expected, observed/expected ratio (o/e) 1.04, 90% interval 0.96 to 1.12.
Homologues: Orthologues: chimpanzee SLC26A9 (99% identical), macaque SLC26A9 (98% identical), pig SLC26A9 (92% identical), dog SLC26A9 (92% identical), mouse Slc26a9 (90% identical), rat Slc26a9 (89% identical), guinea pig SLC26A9 (88% identical), rabbit SLC26A9 (85% identical), tropical clawed frog slc26a9 (64% identical). Paralogues in human: SLC26A6 (33% identical), SLC26A4 (32% identical), SLC26A5 (32% identical), SLC26A3 (32% identical), SLC26A2 (28% identical), SLC26A8 (26% identical), SLC26A1 (25% identical), SLC26A7 (23% identical), SLC26A11 (18% identical).
Diseases named in the same sentence as SLC26A9 in open-access papers:
SLC26A9 is named in the same sentence as 52 diseases in open-access papers, as found by Europe PMC text mining. Sharing a sentence is not in itself a finding about the gene and the disease. The quoted sentences say what the papers report.
cystic fibrosis (16 papers, 2015 to 2026). Autosomal recessive disorder caused by pathogenic variants in the CFTR gene (cystic fibrosis transmembrane conductance regulator), which encodes a chloride and bicarbonate channel expressed in epithelial cells, and follow the diagnosis criteria. "Variants of SLC26A9 were associated with an increased incidence of meconium ileus and diabetes in patients with cystic fibrosis." (PMID 37686084, 2023). "This question is particularly important in light of a potential role of human SLC26A9 to compensate for the loss of CFTR mediated Cl– transport in patients suffering from cystic fibrosis (Balázs and Mall, 2018; Mall and Galietta, 2015)." (PMID 31339488, 2019). "Recently, polymorphisms in the slc26a9 gene were associated with an increased risk of meconium ileus (MI) in infants with cystic fibrosis, which addresses the question regarding the expression and function of Slc26a9 in the intestine." (PMID 30233393, 2018). "Recently, polymorphisms in the slc26a9 gene have been found to be associated with an increased risk for meconium ileus in infants with cystic fibrosis." (PMID 24965066, 2015). "Additionally, based on their possible roles in anion transport, some members of the family, including SLC26A4 and SLC26A9, have been linked to cystic fibrosis as disease modifiers or potential therapeutic targets." (PMID 35204703, 2022). "SLC26A9 has also been implicated in the pathogenesis of bronchiectasis, the widening of airways frequently due to mucous obstruction, a condition often seen in patients with cystic fibrosis." (PMID 26612971, 2015). "Solute carrier family 26, member 9 (SLC26A9) is an epithelial chloride channel that was identified as a genetic modifier of disease severity of cystic fibrosis and other chronic muco-obstructive lung diseases." (PMID 41105627, 2025). "SLC26A9 has gained attention because of its modifier role in the gastrointestinal manifestation of cystic fibrosis." (PMID 36866602, 2023). "Together, our structure takes important steps in elucidating the structural features and regulatory mechanism of SLC26A9, with potential significance in the treatment of cystic fibrosis." (PMID 32818062, 2020). "As a potential target colocalizing with CFTR in cystic fibrosis patients, SLC26A9 is of great value in drug development." (PMID 32818062, 2020). "The solute carrier family 26, member 9 (SLC26A9) is an epithelial chloride channel that is expressed in several organs affected in patients with cystic fibrosis including the lungs, the pancreas, and the intestine." (PMID 30327603, 2018). "Slc26a9 variants were recently found associated with a higher incidence of meconium ileus in cystic fibrosis infants, raising the question whether Slc26a9 is expressed in the intestine and what its functional role is." (PMID 24965066, 2015). "On the basis of different preliminary findings, including the phenotype of SlC26A9-deficient mice and its possible role as a gene modifier of the human phenotype and treatment response, SLC26A9 has emerged as one of the most interesting alternative targets for the treatment of cystic fibrosis." (PMID 35204703, 2022). "In addition, two diffuse idiopathic bronchiectasis-related missense mutations (R575W and V486I) were reported to decrease Cl– transport, suggesting a potential role for SLC26A9 in treating cystic fibrosis-like diseases." (PMID 32818062, 2020). "In the future it may be possible to develop drugs that target SLC26A9 to treat cystic fibrosis and other severe lung diseases." (PMID 31339488, 2019). "Colocalizing with CFTR, SLC26A9 has been proposed as a target for the treatment of cystic fibrosis." (PMID 31339488, 2019). "SLC26A9 was suggested to have a role in inflammatory airway diseases, such as cystic fibrosis and asthma." (PMID 35328418, 2022). "TMEM16A and SLC26A9 attenuate airway inflammation in cystic fibrosis 7, prevent mucus obstruction during airway inflammation and attenuate the intestinal obstructive phenotype in CF mice." (PMID 28963502, 2017).
cystic fibrosis (continued). "SLC26A9 has not been directly linked to disease, but sequencing data identified variants of SLC26A9 that are associated with an increased incidence of meconium ileus or diabetes observed in patients with cystic fibrosis." (PMID 36866602, 2023). "SLC26A9, a constitutively active Cl− transporter, has gained interest over the past years as a relevant disease modifier in several respiratory disorders including Cystic Fibrosis, asthma, and non-CF bronchiectasis." (PMID 34884866, 2021).
Meconium ileus (10 papers, 2015 to 2023). Obstruction of the intestine due to abnormally thick meconium. "Based on GTEx data, the meconium ileus risk alleles are associated with decreased SLC26A9 expression, but increased ATP12A and SLC6A14 expression in the pancreas." (PMID 30807572, 2019). "Sibling and twin studies demonstrated a high heritability for this disease phenotype and a number of genetic studies reported association of SLC26A9 with meconium ileus." (PMID 30327603, 2018). "SLC26A9 is a key candidate in CF as it has been shown to play a pleiotropic role across CF phenotypes, associated with meconium ileus, immunoreactive trypsinogen at birth, pancreatic damage, and CFRD." (PMID 30140228, 2018). "We tested other SLC26A9 variants that had been previously shown in GWAS to contribute to the variability of other phenotypes, such as meconium ileus (rs4077468, rs4077469, rs7419153, rs12047830, rs12741299) and CFRD (rs4077468, rs4077469, rs1874361)." (PMID 30140228, 2018). "How do we reconcile our findings of altered ionic transport in the proximal duodenum of Slc26a9 KO mice with an increased incidence of meconium ileus in CF infants having polymorphisms in the Slc26a9 gene?" (PMID 24965066, 2015). "SLC26A9 appears to have an impact on the extent of intestinal obstruction caused by meconium ileus." (PMID 36866602, 2023). "Furthermore, it is known that variants (SNPs) in the SLC26A9 anion transporter can influence disease severity in the CF lungs and gut (meconium ileus) and, therefore, act as gene modifiers." (PMID 27714410, 2017). "Taken together with previous reports of SLC26A9-associated pancreatic phenotypes we purport that SLC26A9 may provide alternative chloride transport at early developmental stages, and that its contribution to meconium ileus, is at least partly, from the pancreas." (PMID 30807572, 2019). "Moreover, SLC26A9 variants have been previously shown in genome wide association studies (GWAS) to contribute to the phenotype variability of meconium ileus (rs7512462, rs4077468, rs4077469, rs7419153, rs12047830, rs12741299) and CF-related diabetes (CFRD, rs4077468, rs4077469, rs1874361)." (PMID 30140228, 2018). "The associated modifier loci colocalized with expression quantitative trait loci (eQTLs) for ATP12A (p = 3.35x10-8), SLC6A14 (p = 1.12x10-10) and SLC26A9 (p = 4.48x10-5) in the pancreas, even though meconium ileus manifests in the intestine." (PMID 30807572, 2019). "When Cftr−/− mice were crossbred with Slc26a9−/− mice, mortality highly increased, indicating that SLC26A9-mediated anion secretion ameliorates meconium ileus." (PMID 30327603, 2018). "Correlations were found with susceptibility to meconium ileus, Pseudomonas infections and decline in pulmonary function in CF children (SLC9A3; Na+/H+ exchanger) and CF-related diabetes (SLC26A9; Cl−/HCO3− transporter)." (PMID 27714410, 2017).
lung disease (7 papers, 2015 to 2024). "Understanding the various mechanisms of SLC26A9 mutations will be important towards developing therapies that can improve lung diseases such as asthma, CF, and bronchiectasis." (PMID 26612971, 2015). "The allelic variant rs7512462 of the SLC26A9 gene has a pleiotropic effect and is associated with both pancreatic disease and MI, while variant rs3788766 (SLC6A14) is correlated with MI, lung disease, and the age of onset of P. aeruginosa infection." (PMID 34945117, 2021). "Due to its high expression in the lung, numerous studies have investigated the role of SLC26A9 in lung disease." (PMID 26612971, 2015). "Altogether, these data not only highlight the impact of SLC26A9 expression in lung disease and response to CFTR modulator drugs but also motivated our research on the interaction between SLC26A9 and CFTR." (PMID 34884866, 2021).
asthma (5 papers, 2018 to 2024). "In the asthmatic airways of humans, SLC26A9 is overexpressed and genetic variants of SLC26A9 increase risk of asthma." (PMID 38673775, 2024). "Furthermore, three SNPs at 3′ UTR of SLC26A9 were identified that were associated with a risk for childhood asthma, with an odds ratio of 1.48." (PMID 30327603, 2018). "Additionally, polymorphisms in the 3′ UTR of slc26a9 that reduce protein expression in vitro are associated with asthma." (PMID 30233393, 2018). "Indeed, a polymorphism (at rs2282430) in the slc26a9 gene was found to be associated with an increased asthma incidence." (PMID 30233393, 2018). "Additionally, SLC26A9 is associated with asthma and lung inflammation." (PMID 38673775, 2024). "Furthermore, reduced expression of SLC26A9 is linked to asthma in children." (PMID 34884866, 2021). "Membrane localization of SLC26A9 was enhanced in wtCFTR-expressing CFBE airway epithelial cells by the interleukin IL-13, which corresponds to earlier data suggesting upregulation of SLC26A9 function in mouse airways by IL-13 and possibly in asthma." (PMID 35328418, 2022). "Notably, airways of asthma patients showed normal apical localization of SLC26A9, which even appeared somewhat stronger in some images, when compared to non-asthmatic airways." (PMID 35328418, 2022). "Finally, the present results support a protective function of SLC26A9 in asthmatic lungs and attach a beneficial role to IL-13, which is found to be enhanced in asthma." (PMID 35328418, 2022). "Thus, an upregulation of SLC26A9-dependent Cl− secretion may help to prevent mucus obstruction in asthma." (PMID 35328418, 2022). "The data suggest an upregulation of SLC26A9-dependent chloride secretion in asthma, but not in the presence of F508del-CFTR." (PMID 35328418, 2022). "In airways of asthma patients, we found normal expression of SLC26A9, and in some sections, SLC26A9 staining appeared somewhat enhanced (not shown)." (PMID 35328418, 2022). "The present results support a role of SLC26A9 for airway chloride secretion in asthma, which may not be detectable in airways of CF-patients carrying the F508del-CFTR allele." (PMID 35328418, 2022). "Third, numerous genetic association studies and investigations utilizing genetically modified mouse models supported an important role of SLC26A9 in the pathophysiology of several organ manifestations in CF, as well as other chronic lung diseases such as asthma and non-CF bronchiectasis." (PMID 30327603, 2018).
bronchiectasis (4 papers, 2015 to 2021). Segmental, irreversible dilation of the bronchial tree resulting in the accumulation of secretions which leads to obstruction. "Thus, loss of SLC26A9, in the setting of CFTR loss, may result in reduced airway surface liquid hydration, mucous blockage, and consequent bronchiectasis." (PMID 26612971, 2015).
diabetes (4 papers, 2019 to 2026). "We previously used the SLC26A9 variant rs7512462 as an instrumental variable in a Mendelian Randomization (MR) study to assess whether damage to the exocrine pancreas is a causal contributor to CF-related diabetes." (PMID 30807572, 2019). "Genotyping revealed high-risk diabetes and CF-modifier variants: rs7903146 TT (TCF7L2) and rs4077468 GG (SLC26A9)." (PMID 42022521, 2026).
gastric cancer (4 papers, 2022 to 2025). A primary or metastatic malignant neoplasm involving the stomach. "Our previous study found that downregulation of SLC26A9 is involved in the occurrence of gastric cancer, which is the first evident to show that SLC26A9 is involved in the occurrence of gastric cancer." (PMID 38461207, 2024). "SLC26A9 deletion resulted in the dysdifferentiation of stem and progenitor cells in an inflammatory milieu, leading to gastric cancer in mice." (PMID 37719006, 2023). "We found that SLC26A9 functions as Cl- channel and plays an important role in gastric acid secretion and is also involved in the regulation of cell proliferation and migration, as well as the formation of gastric cancer." (PMID 38461207, 2024). "Thus, the deletion of SLC26A9 shows significant tumorigenicity and hastens the progression of gastric cancer." (PMID 37719006, 2023). "Here, we describe morphological and molecular alterations in gastric mucosa of slc26a9−/− mice and in selective parietal cell-deleted slc26a9fl/fl/Atp4b-Cre mice and correlate SLC26A9 expression levels with morphological and clinical parameters in a cohort of gastric cancer (GC) patients." (PMID 35426084, 2022). "The study also found that the expression of Slc26a9 was gradually downregulated in human gastric diseases, from chronic gastritis to metaplasia, from GPL to early gastric cancer." (PMID 37719006, 2023).
intestinal obstruction (3 papers, 2015 to 2023). Blockage of the normal flow of the intestinal contents within the bowel. "Slc26a9 deletion strongly reduces the survival of CFTR KO mice, particularly in the weaning phase, where the mice die of intestinal obstruction." (PMID 24965066, 2015).
Airway obstruction (2 papers, 2022 to 2025). Obstruction of conducting airways of the lung. "Histology, immunohistochemistry, and micro-computed tomography imaging studies identified airway obstruction with MUC5B-positive mucus plugs in neonatal Slc26a9-/- mice." (PMID 41105627, 2025).
breast carcinoma (2 papers, 2014 to 2025). "Especially basal breast cancers are distinct from the other subtypes, with markedly different expression patterns of many of these proteins compared to the other subtypes, including an apparent strong and consistent upregulation of SLC26A9." (PMID 24795638, 2014). "Another example is the expression pattern of SLC26A9 and CAIX in breast cancer, which is strikingly similar, with high levels in basal and triple-negative breast cancers only." (PMID 24795638, 2014).
chronic gastritis (2 papers, 2018 to 2022). Inflammation of the stomach that is chronic in nature. "We also found that Slc26a9 expression is progressively downregulated in human gastric disease from chronic gastritis to metaplasia and from well-differentiated GC to cancer with a low differentiation grade." (PMID 35426084, 2022).
colorectal cancer (2 papers, 2024 to 2026). A primary or metastatic malignant neoplasm that affects the colon or rectum. "We explored the role of SLC26A9 in colorectal cancer (CRC) and its related mechanisms through clinical samples from CRC patients, CRC cell lines and mouse models." (PMID 38461207, 2024). "A heatmap of the top 50 differentially expressed genes was generated, highlighting that genes such as SPRR family members, MUC6, KRT family genes, SLC26A9, MMP7, PRSS56, and SFRP1 were highly expressed in the colorectal cancer group." (PMID 41595533, 2026). "In our study, TCGA analysis revealed that genes such as those from the SPRR family, MUC6, KRT family, SLC26A9, MMP7, PRSS56, and SFRP1 were highly expressed in the colorectal cancer group." (PMID 41595533, 2026).
gastric disease (2 papers, 2021 to 2022). "Importantly, KO mouse models for SLC26A7, SLC26A9, and SLC4A2 were described with gastric achlorhydria, which demonstrates that alterations found in our patients might explain gastric disease." (PMID 34944008, 2021).
schizophrenia (2 papers, 2018 to 2021). A major psychotic disorder characterized by abnormalities in the perception or expression of reality. "Nevertheless, a genome-wide pharmacogenomics study investigating neurocognition reported that rs11240594 at slc26a9 mediates the effects of olanzapine on processing speed, indicating that slc26a9 may be a novel candidate gene for antipsychotic responses in schizophrenia." (PMID 30233393, 2018). "However, an increasing number of functional studies have shown that Slc26a9 may also be involved in some non-CF-related diseases, such as Sjögren’s syndrome, schizophrenia and unreported diseases, including duodenal ulcers, Type 2 diabetes and hypertension." (PMID 30233393, 2018).
adenoma (1 paper, 2024). A neoplasm arising from the epithelium. "We observed that SLC26A9 was expressed at low levels in the cytoplasm of adjacent tissues, polyps and adenomas but was significantly increased in colorectal adenocarcinoma." (PMID 38461207, 2024). "This study showed that the expression of SlC26A9 gradually increased during the process of CRC formation (polyps, adenomas and CRC)." (PMID 38461207, 2024).